CD163 (CD163 molecule)
Diseases named in the same sentence as CD163 in open-access papers (continued):
Sharing a sentence is not in itself a finding about the gene and the disease.
Atrophy (1 paper, 2025). Any weakening or degeneration, especially through lack of use. "Based on this classification, patients with higher levels of glomerular CD68+ more commonly had severe interstitial fibrosis/tubular atrophy (p = 0.030), higher median number of interstitial CD68+ cells (p = 0.007), and higher median number of CD163+ cells in the glomerulus (p = 0.019)." (PMID 40338344, 2025).
basal cell carcinoma (1 paper, 2024). A carcinoma involving the basal cells. "Our finding of further increased VEGF-A levels in VSCC cells cocultured with CD163+ TAMs is supported by the previous observation that TAMs can induce the p38 MAPK/NFκB/COX-2–dependent secretion of VEGF-A in basal cell cancer cells." (PMID 38407373, 2024).
bipolar disorder (1 paper, 2021). A disorder of the brain that causes unusual shifts in mood, energy, activity levels and the ability to carry out day-to-day tasks. "We also found increased CD163, CD14 and ICAM1 mRNAs in high compared to low inflammation bipolar disorder (39–104%, all post hocp ≤ 0.008)." (PMID 34911938, 2021). "CD163+ cell counts did not significantly differ between high inflammation bipolar disorder and low inflammation controls nor low inflammation bipolar disorder cases (all p > 0.73)." (PMID 34911938, 2021).
bone tumor (1 paper, 2024). "CD68+/CD163+ M2-like immunosuppressive macrophages were also not distinguished between primary breast and bone tumor and stromal tissue segments." (PMID 38193534, 2024).
brucellosis (1 paper, 2017). Brucellosis is a bacterial infection that spreads from animals to people via unpasteurized dairy products or by exposure to contaminated animal products or infected animals. "Moreover, 3-MA restored CD80 and CD86 expression levels on M1 macrophages, and CD163 and CD206 expression levels on M2 macrophages in brucellosis patients." (PMID 28659924, 2017).
calcification (1 paper, 2023). Process by which organic tissue becomes hardened by the physiologic deposit of calcium salts. "Last, we identified an inverse relationship between a human CD163 polymorphism (i.e., rs7136716) and dense coronary calcification development in African Americans who suddenly died with coronary plaque rupture." (PMID 36719758, 2023).
cat-scratch disease (1 paper, 2012). Cat scratch disease is an infectious illness caused by the bacteria bartonella (Bartonella henselae). "Furthermore, inflammatory cells such MBLs, CD68+, CD163+, CD204+ macrophages, S-100+, Langerin+, CD83+, CD163+ dendritic cells and T lymphocytes can be regarded as playing an important role for granuloma formation in tularemia, as in cat scratch disease." (PMID 22588497, 2012).
chloroma (1 paper, 2025). "Immunophenotyping for monocytic markers, such as CD68, CD163, and MPO, can distinguish CNS chloroma from other neoplastic or inflammatory processes." (PMID 40951121, 2025).
cholangitis (1 paper, 2024). An acute or chronic inflammatory process affecting the biliary tract. "The M2 ratio, defined as the proportion of M2 macrophages (CD163-positive cells), was correlated inversely with the occurrence of postoperative cholangitis (AUC: 0.7602)." (PMID 38318455, 2024).
cholestasis (1 paper, 2021). Impairment of the bile flow caused by obstruction within the liver, or outside the liver in the bile duct system. "We conclude that short-term cholestasis leads to a pro-inflammatory reaction mediated by CD80+ cells, while chronic tissue damage is associated with a shift to an increasing number of MDMs with a dominant anti-inflammatory CD163+ cell fraction." (PMID 33918803, 2021).
cholesteatoma (1 paper, 2022). A pathologic process characterized by the proliferation of keratinizing squamous epithelium resulting in the accumulation of keratin and cells in the middle ear and/or mastoid. "In the present study, human cholesteatoma specimens acquired during tympanomastoidectomy were retrospectively retrieved and immunohistochemically characterized using a combination of antibodies labeling M1 macrophages (CD80), M2 macrophages (CD163), and total macrophages (CD68)." (PMID 36013064, 2022).
chronic GVHD (1 paper, 2019). "Plasma CD163, a macrophage scavenger receptor, has been correlated with a higher cumulative incidence of chronic GVHD in a cohort of 167 patients." (PMID 33511333, 2019). "Increased CD163 with exposure to the anti-inflammatory cytokine IL-10 may contribute to M2 macrophage recruitment and chronic GVHD pathogenesis." (PMID 33511333, 2019).
cleft palate (1 paper, 2023). Cleft palate is a fissure type embryopathy that affects the soft and hard palate to varying degrees. "The presence of CD-163-positive macrophages further maintains the idea of the role of local immunity in patients with cleft palates." (PMID 37508659, 2023).
colorectal adenocarcinoma (1 paper, 2025). The most common type of colorectal carcinoma. "The data showed a clear colocalization of CD163 and AKR1B1 in macrophages both localized in the subepithelial portion of lamina propria in nonneoplastic colon mucosae and tumor stroma of colorectal adenocarcinoma." (PMID 40396420, 2025).
cryptorchidism (1 paper, 2025). The failure of one or both testes of a male fetus to descend from the abdomen into the scrotum during the late part of pregnancy. "The MSC secretome contributes to the decrease in the number of CD163+ M2 macrophages in the interstitium in cryptorchidism model at late stages, 3 months after the MSC secretome injection." (PMID 40416498, 2025). "At late stage of cryptorchidism, 3 months after the MSC secretome administration, there was observed the decrease in the number of CD163+ M2 macrophages in the animal testicles." (PMID 40416498, 2025).
cutaneous leishmaniasis (1 paper, 2025). Leishmaniasis affecting the skin. "CD68+ and CD163+ macrophages were more abundant in cutaneous leishmaniasis (p < 0.0001 and p < 0.05)." (PMID 40947759, 2025). "In cutaneous leishmaniasis, CD68+ macrophages correlated positively with inflammasome markers, whereas in mucocutaneous leishmaniasis, CD163+ cells showed strong negative correlations with IL‐1β and caspase‐1." (PMID 40947759, 2025).
cystic kidneys (1 paper, 2016). "Initially, individual antibodies (anti-CD163 or anti-phospho-STAT3) were used for immunohistochemical staining of adjacent serial sections of ADPKD cystic kidneys to look for interstitial phospho-STAT3-positive cells, specifically in macrophage-rich areas." (PMID 27491076, 2016). "Sections of ADPKD cystic kidneys were also prepared for immunofluorescence co-staining for CD163 and phospho-STAT3." (PMID 27491076, 2016).
dementia with Lewy bodies (1 paper, 2025). "In the specific case of neuronal synucleinopathies, including PD, Parkinson’s disease dementia (PDD), and dementia with Lewy bodies (DLB), there is an observed increase in the density of perivascular macrophages expressing CD163." (PMID 40510352, 2025).
dermatitis (1 paper, 2020). An inflammatory process affecting the skin. "Further studies could provide novel insights into the functional roles of CD163 and Arg1 during oxazolone-induced dermatitis." (PMID 33122966, 2020).
Dermatofibromas (1 paper, 2025). "Dermatofibromas consist of dermal fibroblasts and histiocytes with FXIIIA, CD163, and CD68 positivity, whereas." (PMID 41446319, 2025).
dysferlinopathy (1 paper, 2023). "CD163 plays a role in the regulation of inflammation in dysferlinopathy." (PMID 37686363, 2023).
eczema (1 paper, 2025). "Triple marker combinations that included CD63 and/or CD163 were each somewhat less frequent in number; however, together they were the most frequent DC populations in eczema (grey bars), and significantly more prevalent than in Pso (black bars)." (PMID 41009640, 2025). "For example, the marker combination CD14, CD63, and CD163 was 4.4-fold higher in eczema compared with Pso (~35 cells/mm2 vs. ~8 cells/mm2), and the marker combination CD11c, CD63, and CD163 was 8.4 fold higher (~25 cells/mm2 vs. 3 cells/mm2) (blue box)." (PMID 41009640, 2025). "While in Pso a monocyte-derived DC (CD14+CD1a+CD11c+) predominated, possibly a Langerhans cell (LC)-like DC, eczema displayed a marker combination of a seemingly more differentiated monocyte-derived DC (CD14+CD63+CD163+), potentially a DC3 cell type." (PMID 41009640, 2025). "In summary, CD14+ positive cells harbouring DC markers (CD11c, CD1a) in combination with CD63 and/or CD163 were far more present in eczema compared with Pso." (PMID 41009640, 2025). "The differentiation of DC in eczema is potentially induced by bacterial-derived antigens (likely from Staphylococcus aureus), eventually leading to the expression of CD163 and CD63, although the latter marker has been described as being expressed on immature DCs." (PMID 41009640, 2025). "While Pso cells with DC markers maintained a CD14+, potentially LC-like phenotype (CD14+CD1a+CD11c+), cells in eczema displayed a marker combination that included CD163 and/or CD63, hinting at a more differentiated DC that may constitute a DC3 subtype, as previously suggested." (PMID 41009640, 2025). "Supporting this conclusion, the marker combinations CD11c, CD63, CD163 and CD14, CD63, CD163 were almost exclusively found in eczema." (PMID 41009640, 2025). "Conversely, in eczema these cells additionally expressed CD63 and CD163 in various combinations with CD1a and CD11c." (PMID 41009640, 2025). "For eczema and Pso, the appearance of CD63 and/or CD163 in combination with CD14 and/or CD1a and/or CD11c in eczema was most discriminatory." (PMID 41009640, 2025). "However, marker combinations that included CD63 and/or CD163 were comparably present (ratios 15–20:1), making these marker combinations representative for eczema but not for Pso." (PMID 41009640, 2025). "In summary, the appearance of CD63 and/or CD163 on CD14+ and/or CD1a/CD11c+ cells were most characteristic and distinctive for eczema skin, whereas the same cells were lacking CD63/CD163 in psoriatic skin." (PMID 41009640, 2025).
endometrial tumors (1 paper, 2023). "Regarding low- and high-grade endometrial tumors’ regional draining nodes, the former showed lower S100A8/A9 (2.273 ± 2.947 vs. 10.154 ± 6.543, p = 0.0001) and CD163 (5.136 ± 6.198 vs. 9.077 ± 8.46, p = 0.0505) values." (PMID 36835583, 2023). "Regarding regional draining nodes in low- and high-grade endometrial tumors, the former showed lower S100A8/A9 and CD163 values." (PMID 36835583, 2023).
epithelioid mesothelioma (1 paper, 2014). "In conclusion, CD163/CD68 ratio was found to be a prognostic marker in a limited number of epithelioid mesothelioma patients, but not a predictive marker for outcome after surgery." (PMID 25192022, 2014). "Our data revealed that the CD163/CD68 ratio is a potential prognostic marker in epithelioid mesothelioma patients independent of treatment but cannot be used as a predictive marker for outcome after surgery." (PMID 25192022, 2014).
fetal growth restriction (1 paper, 2025). A fetus that does not grow beyond the 10th percentile of conventionally accepted weight for gestational age. "In human placental macrophages, CD163 is recognized as a distinctive surface marker, and an increased number of CD163+ cells has been observed in villous and intervillous compartments of placentas from pregnancies with fetal growth restriction." (PMID 41303355, 2025).
fibrous tumors (1 paper, 2020). "On the other hand, we found a higher rate of CD163+ cell infiltration in fibrous tumors than in non-fibrous tumors (median: 26 cells; range 19–39 vs. 49 cells; range 35–73, P < 0.05)." (PMID 33081727, 2020).
HCMV infection (1 paper, 2020). "In accord with our previous study, HCMV infection increased the expression of the M2 marker, CD163, as well as an additional M2 marker, CD16." (PMID 32560319, 2020).
Hearing impairment (1 paper, 2025). A decreased magnitude of the sensory perception of sound. "Our finding of elevated levels of TNF-α, IL-2R, CD163, eotaxin, and HGF in VS-CM being significantly associated with hearing impairment in patients with VS suggests that inflammatory pathways and immune cell activation are key contributors to VS-induced hearing loss." (PMID 39923035, 2025).
hemochromatosis (1 paper, 2024). A disorder of iron metabolism characterized by a triad of HEMOSIDEROSIS; LIVER CIRRHOSIS; and DIABETES MELLITUS. "Notably, the major biological process for expansion was acute-phase response (GO:0006953), involving the families for differentiation 163 (CD163) and hemochromatosis (HFE), displaying a fold enrichment exceeding." (PMID 38658744, 2024).
hepatitis C infection (1 paper, 2019). "Furthermore, CD163+ monocytes can secrete both pro- and anti-inflammatory cytokines such as TNF-α and IL-4 during Leishmania and hepatitis C infection, which might interfere in instructing T cells and inhibit the killing of intracellular pathogens." (PMID 31779590, 2019).
hepatoblastoma (1 paper, 2022). Hepatoblastoma (HB) is a malignant hepatic tumor and is the most common pediatric liver cancer. "In conclusion, a high density of CD163‐positive TAMs was seen in embryonal components of hepatoblastoma cases, and Brd4‐induced IL‐34 production was suggested to induce infiltration of TAMs in embryonal components." (PMID 35132816, 2022). "In the present study, we showed potential protumor functions of CD163‐positive M2‐like macrophages in hepatoblastoma cases." (PMID 35132816, 2022). "CD163 and IL‐10 expression was significantly elevated by CM from hepatoblastoma cell lines." (PMID 35132816, 2022).
Hypercalcemia (1 paper, 2025). An abnormally increased calcium concentration in the blood. "In contrast, using renal tissue from IgG4-RD patients without hypercalcemia as controls, showed no co-localization of CD163 and 1α-hydroxylase in the areas." (PMID 41451224, 2025).
Hypercholesterolemia (1 paper, 2024). An increased concentration of cholesterol in the blood. "The LLV and CCL2/MCP‐1 interaction was borderline significant, while the interaction between LLV and CD163 was statistically significant in the association with hypercholesterolemia." (PMID 39189824, 2024).
hyperlipidemia (1 paper, 2025). "CD163 expression in cardiac tissue is also associated with hyperlipidemia and cellular stemness." (PMID 40630963, 2025).
hypersensitivity pneumonitis (1 paper, 2017). Hypersensitivity pneumonitis (HP) is a pulmonary disease with symptoms of dyspnea and cough resulting from the inhalation of an antigen to which the subject has been previously sensitized. "Our results suggest that expression of CD206, CD163, CCL2 and TGFβ is high in IPF patients as compared to a chronic inflammatory condition that does not progress to fibrosis, hypersensitivity pneumonitis." (PMID 28817691, 2017).
Hypokalemia (1 paper, 2018). An abnormally decreased potassium concentration in the blood. "There were more CD163 and CD68 positive cells infiltration in tubulointerstitial injury of pSS, especially in patients with hypokalemia." (PMID 30396309, 2018).
hypophysis (1 paper, 2016). "The identification of abundant macrophages bearing the M2-marker CD163 and abundant fibrosis in this case raises the possibility that postpartum IGH may involve a T helper 2 (Th2) response to autoantigens in the hypophysis." (PMID 27642532, 2016).
IgG4-related disease (1 paper, 2025). "In IgG4-related disease (IgG4-RD), CD163+ M2 Mφs promote fibroblast activation and fibrosis by releasing profibrotic cytokines (e.g., IL-33, TGF-β) through the TLR7/IRAK4/NF-κB pathway." (PMID 41164198, 2025). "In IgG4-related disease, TLR7+ CD163+ M2 Mφs directly drive fibrosis by secreting TGF-β and other profibrotic factors via the TLR7/IRAK4/NF-κB pathway." (PMID 41164198, 2025).
intrahepatic cholangiocarcinoma (1 paper, 2019). A carcinoma that arises from the intrahepatic bile duct epithelium in any site of the intrahepatic biliary tree. "In intrahepatic cholangiocarcinoma (ICC), patients with high counts of CD163+ M2 macrophages showed poor disease-free survival." (PMID 31480382, 2019).
Intraventricular hemorrhage (1 paper, 2020). Bleeding into the ventricles of the brain. "Neuronal degeneration following intraventricular hemorrhage, and particularly neuronal death in the hippocampus, may be due to hemoglobin pro-apoptotic properties through the up-regulation of Jun N-terminal kinases (JNK) and CD163." (PMID 32751801, 2020).
iron deficiency (1 paper, 2023). "CSF levels of macrophage activation marker-soluble CD163 (sCD163), iron deficiency marker ferritin, and soluble form of interleukin-2 receptor α (sIL-2Rα) were measured by enzyme-linked immunosorbent assay at two points (17 h and 72 h)." (PMID 36901893, 2023).
iron metabolism disorder (1 paper, 2023). "In macrophages, the up-regulation of Cav-1 promoted the expression of HO-1 in CD68+CD163+ macrophages, which facilitated the degradation of red blood cells into Fe2+ within macrophages and accelerated iron metabolism disorder in NAFLD." (PMID 37941054, 2023).
Kaposi's sarcoma (1 paper, 2015). A malignant neoplasm characterized by a vascular proliferation which usually contains blunt endothelial cells. "Linking a CD163-antibody to DoxilTM, a registered liposomal doxorubicin formulation against Kaposi’s sarcoma, has been shown to specifically kill CD163-expressing cells." (PMID 26111002, 2015).
keratoacanthoma (1 paper, 2024). A dome-shaped, rapidly growing skin lesion composed of well differentiated squamous cells. "A study comparing cSCC and keratoacanthoma samples revealed the presence of CD163+ macrophages and MMP-9+ cells only in cSCC samples." (PMID 38248804, 2024).
kidney cancer (1 paper, 2018). Primary or metastatic malignant neoplasm involving the kidney. "The high CD163+/CD206+ cancer group consisted of 4 cases (one pancreas, two prostate, one kidney cancers) with 11.5–26.3% of the CD163 mask comprised of CD163+/CD206+ pixels." (PMID 30619287, 2018).
latent infections (1 paper, 2022). "In line with our MIBI-TOF analysis, differential expression of genes associated with regulatory myeloid cells (e.g., PD-L1, PD-L2, CD11b, CD11c and CD163) or T cell immune checkpoint (e.g., PD-1 and CTLA4) delineated active from latent infections." (PMID 35058616, 2022).
localized scleroderma (1 paper, 2012). Localized scleroderma is the skin localized form of scleroderma characterized by fibrosis of the skin causing cutaneous plaques or strips. "Activated M2 macrophages (CD163 positive) have also been found in the skin of patients with localized scleroderma and have been implicated as a possible source of profibrotic cytokines." (PMID 22913887, 2012).
Lyme borreliosis (1 paper, 2019). "In comparison to a healthy control group with a median of 29.96%, the percentage of CD163 positive cells is significantly lower in Lyme borreliosis patients (median: 5%) (Mann-Whitney-U test p < 0.0001)." (PMID 31366164, 2019). "However, when distinguishing functional subgroups of circulating monocytes (M1 pro-inflammatory versus M2 anti-inflammatory monocytes), the majority of Lyme borreliosis patients presented with low to very low amounts of CD163+ M2 macrophages." (PMID 31366164, 2019).
lymphopenia (1 paper, 2021). Reduction in the number of lymphocytes. "As observed in previous studies, our cohort of patients exhibit a profound lymphopenia and alterations of the myeloid compartment, with an increase of circulating “dysfunctional” CD14+CD163+ and CD14+HLA-DRlow monocytes as compared to controls." (PMID 34322128, 2021).
meningeal carcinomatosis (1 paper, 2025). "Similarly, polarization analysis revealed a significant association between low CD163 expression in the tumor nest of brain metastases and the presence of meningeal carcinomatosis (p = 0.04)." (PMID 40510346, 2025). "Low expression of CD68 and CD163 in brain metastases correlated with the presence of meningeal carcinomatosis." (PMID 40510346, 2025).